PALMD (palmdelphin)
Synonyms: C1orf11; PALML; FLJ20271
Tractability: PROTAC: UniProt records ubiquitination sites on it; ubiquitination databases record sites on it; its protein half-life has been measured.
Gene: Protein-coding gene on chromosome 1 (99,645,499 to 99,695,178, forward strand). Ensembl gene ENSG00000099260.
Subcellular location: Cytoplasm; Cell projection, dendrite; Cell projection, dendritic spine
Subcellular location (Human Protein Atlas): Actin filaments; Focal adhesion sites; Plasma membrane
Gene Ontology:
Molecular function: protein binding
Biological process: regulation of cell shape
Cellular component: actin cytoskeleton; cytoplasm; dendrite; dendritic spine; membrane
Genetic constraint (gnomAD): Loss-of-function variants: 20 observed, 30.17 expected, observed/expected ratio (o/e) 0.66, 90% interval 0.47 to 0.96. The upper end of that interval is the gene's LOEUF score, 0.96, which puts it in group 4 of 6, group 1 being the genes least tolerant of losing a copy. Missense variants: 448 observed, 471.79 expected, observed/expected ratio (o/e) 0.95, 90% interval 0.88 to 1.03. Synonymous variants: 180 observed, 169.42 expected, observed/expected ratio (o/e) 1.06, 90% interval 0.94 to 1.2.
Homologues: Orthologues: chimpanzee PALMD (98% identical), macaque PALMD (98% identical), dog PALMD (85% identical), rabbit PALMD (85% identical), guinea pig PALMD (85% identical), pig PALMD (83% identical), mouse Palmd (81% identical), rat Palmd (78% identical), tropical clawed frog palmd (46% identical), zebrafish palmda (30% identical), zebrafish palmdb (12% identical). Paralogues in human: PALM (23% identical), PALM2AKAP2 (17% identical), PALM3 (17% identical).
Diseases named in the same sentence as PALMD in open-access papers:
PALMD is named in the same sentence as 13 diseases in open-access papers, as found by Europe PMC text mining. Sharing a sentence is not in itself a finding about the gene and the disease. The quoted sentences say what the papers report.
aortic stenosis (2 papers, 2022). Aortic valve stenosis is a aortic valve disease caused by the incomplete opening of the aortic valve. "Stratifying by aortic valve morphology, PALMD rs6702619 and IL6 rs1800795 polymorphisms were associated with aortic stenosis in tricuspid aortic valve (TAV) patients only." (PMID 36337884, 2022). "In the genotyping of 578 individuals, we found significant association between PALMD and IL6 polymorphisms and aortic stenosis in patients with tricuspid aortic valve, independently of other potentially confounding variables such as age and dyslipidemia." (PMID 36337884, 2022). "PALMD is considered to be a target of aortic stenosis, and there are few studies." (PMID 35494064, 2022).
aortic valve disease (2 papers, 2020 to 2022). "Patients with aortic valve disease were genotyped for PALMD rs6702619, LPA rs10455872, and IL6 rs1800795 polymorphisms and circulating levels of interleukin-6 (IL-6) were measured." (PMID 36337884, 2022). "A pheWAS approach on a wide range of health conditions showed that genetically-determined expression of PALMD in the aortic valve is specifically associated with aortic valve-related outcomes such as CAVS, aortic valve disorders and aortic valve replacement/repair." (PMID 32859967, 2020).
aortic valve stenosis (2 papers, 2020 to 2022). Aortic valve stenosis (AVS) is a condition characterized by narrowing of the heart's aortic valve opening. "The causal variant and the mechanism by which it affects PALMD expression and aortic valve stenosis remain to be validated in experimental models." (PMID 32859967, 2020). "In our study, we have confirmed that polymorphisms in PALMD and IL6 genes are associated with aortic valve stenosis and the latter one, in addition, with higher circulating levels of IL-6." (PMID 36337884, 2022). "Other than diagnosis and procedures for aortic valve stenosis, there was no phenotype significantly associated with genetically-determined PALMD expression in the aortic valve in the UK Biobank after correction for multiple testing." (PMID 32859967, 2020).
aortic valve calcification (1 paper, 2025). "Though rs3818852 has no previous associations, PALMD has been associated with complex traits from different phenotypic domains such as aortic valve calcification and the vaginal microbiome." (PMID 41282258, 2025).
atrial fibrillation (1 paper, 2020). A disorder characterized by an electrocardiographic finding of a supraventricular arrhythmia characterized by the replacement of consistent P waves by rapid oscillations or fibrillatory waves that vary in size, shape and timing and are accompanied by an irregular ventricular response. "We show that the association with CAVS is specific to the aortic valve and that PALMD expression in other tissues could be associated with atrial fibrillation." (PMID 32859967, 2020). "Using previously reported aortic valve expression data and genotypes from large cohorts, they find a strong and specific association between genetically-determined PALMD expression in the aortic valve and CAVS as well as a novel association with atrial fibrillation in non-cardiac tissues." (PMID 32859967, 2020).
cardio-embolic stroke (1 paper, 2020). "Also, we found that predicted expression of PALMD in subcutaneous adipose tissue was associated with cardio-embolic stroke (z = 3.7, P = 0.00024), but the probability of colocalization was low (PP4 = 5.4%)." (PMID 32859967, 2020).
ischemic stroke (1 paper, 2020). A stroke disorder caused by obstruction of blood flow to the brain, due to thrombotic (local blood clot formation) or embolic (due to a blood clot or other material traveling from another site) event. "Using the false-discovery rate threshold, there was a significant inverse association between PALMD genetically-determined expression in the aortic valve and ischemic stroke (z = −3.1, P = 0.0019), with a low probability of colocalization (PP4 = 15.7%)." (PMID 32859967, 2020).
liver cancer (1 paper, 2022). An epithelial or non-epithelial malignant neoplasm that arises from the liver. "In addition, one study has reported that emodin inhibits the growth of liver cancer cells, and 15 representative genes such as PALMD (down-regulated) are considered to be related to the response to emodin treatment." (PMID 35494064, 2022).
psoriasis (1 paper, 2023). An autoimmune condition characterized by red, well-delineated plaques with silvery scales that are usually on the extensor surfaces and scalp. "However, Coiled-coil domain containing 3 (CCDC3) and palmdelphin (PALMD) have not been reported as known factors contributing to the development or progression of psoriasis." (PMID 38132145, 2023).
tumor (3 papers, 2022 to 2024). "CTF1 and RAPGEF3 were previously reported to be parts of gene signatures related to tumor microenvironment and immune system, with the first seen downregulated and methylated in BAP1 mutated samples; PALMD was found to have low expression in metastatic UM tissues, and GSTA3 in low-survival patients." (PMID 38339073, 2024).
cardiovascular disorder (1 paper, 2023). A disease involving the cardiovascular system. "Both ABO and PALMD are widely expressed in tissues, and both harbor variants associated with cardiovascular disorders." (PMID 37884687, 2023).
PALMD also shares sentences with these, for which no sentence is quoted: osteosarcoma (2 papers); dyslipidemia (1).